MYCN (MYCN proto-oncogene, bHLH transcription factor)
Diseases named in the same sentence as MYCN in open-access papers (continued):
Sharing a sentence is not in itself a finding about the gene and the disease.
diabetes (3 papers, 2014 to 2025). "Through the biological effects of MYCN, corresponding research will be carried out to clarify new ideas for the treatment of diabetes based on the mechanism of MYCN on methylation and ferroptosis." (PMID 39966875, 2025). "In IF, the expression trends of MYCN in diabetes tissues were consistent with the Western blot and IHC results." (PMID 37904700, 2023). "The overexpression of MYCN makes mouse beta cells enter G1 cell cycle, which is the growth and differentiation stagnation, leading to the growth and differentiation obstacle of beta cells and diabetes." (PMID 39966875, 2025). "Furthermore, because diabetes is a heritable condition, studying MYCN and CD44 expression in parents and children with a family history of diabetes may offer new avenues for diabetes genetic research." (PMID 37904700, 2023). "However, studies related to MYCN and diabetes are still scarce." (PMID 37904700, 2023). "We discovered that MYCN may have a protective effect against diabetes, and its overexpression may alleviate diabetes, reduce the occurrence of diabetes complications such as diabetic foot, and mitigate diabetes malignancy." (PMID 37904700, 2023). "Thus, the destabilization of MYC/MYCN by metformin and phenformin and the ability of metformin to upregulate tumor suppressor genes may partly explain why these diabetes drugs protect against cancer incidence and mortality." (PMID 24190252, 2014).
pancreatic neuroendocrine tumor (3 papers, 2008 to 2023). Pancreatic endocrine tumor, also known as pancreatic neuroendocrine tumor (PNET), describes a group of endocrine tumors originating in the pancreas that are usually indolent and benign, but may have the potential to be malignant. "When solitary MYCN expression is driven under the control of the hGFAP promoter, transgenic mice (hGFAP-cre::lsl-MYCN) develop neuroendocrine tumors of the pancreas and pituitary adenomas." (PMID 37407554, 2023). "Interestingly, 3 out of 9 human pancreatic neuroendocrine tumors expressed MYCN, supporting the similarity of the mouse tumors to the human system." (PMID 27769070, 2016).
pheochromocytoma (3 papers, 2012 to 2025). "In pheochromocytomas, a MYCN proto‐oncogene (MYCN)‐positive cluster correlates with poorer survival." (PMID 40190189, 2025). "MYCN‐positive clusters in pheochromocytomas indicated poorer survival." (PMID 40190189, 2025). "RASSF5A mRNA expression have also been reported as frequently down-regulated in NB and pheochromocytoma primary tumors and lower RASSF5A expression was seen in NB tumors without MYCN-amplification compared to MYCN-amplified tumors." (PMID 22695170, 2012).
prostate tumors (3 papers, 2019 to 2023). "AKT1/MYCN-mediated progression was also associated with the development of invasive metastatic castration-resistant prostate tumors." (PMID 37370720, 2023). "Genetically modified mice, Pb-Cre+/− Ptenfl/fl LSL-MYCN+/+, develop prostate tumours in 100% of offspring compared with littermates that lack MYCN expression (Pb-Cre+/− Ptenfl/fl LSL-MYCN−/−)." (PMID 34445233, 2021).
renal cell carcinoma (3 papers, 2018 to 2025). "MYCN gene mutations are predominantly found in neurogenic cancers and are infrequently observed in renal cell carcinoma." (PMID 40177240, 2025). "Research has indicated that the silencing of MYCN can promote cell migration, while the presence of MYCN and CDKN2A correlates with tumor stage, metastasis, and overall survival in renal cell carcinoma." (PMID 40177240, 2025). "In renal cell carcinoma, down-regulation of CXXC4 by siRNA resulted in the up-regulation of some cellular proliferation related genes (FGF18, EGR1, and MYCN), the down-regulation of apoptosis inhibitor proteins BIRC7 and XAF1, and some other important tumor progression factors." (PMID 30042169, 2018).
thyroid cancer (3 papers, 2013 to 2023). "It was also co-expressed with the MYCN protein in some primary human cancers, including thyroid cancer." (PMID 24391509, 2014).
anaplastic ependymoma (2 papers, 2019 to 2023). Anaplastic ependymoma is a rare, malignant type of ependymoma that most often arises in the supratentorial region of the brain of children and young adults and that manifests with variable symptoms including headaches, nausea, vision impairment, memory loss and difficulty walking. "MYCN-amplified anaplastic ependymomas are locally aggressive, recurrent, and have a high risk of iatrogenic injury." (PMID 37854648, 2023).
anemia (2 papers, 2013 to 2025). A reduction in the number of red blood cells, the amount of hemoglobin, and/or the volume of packed red blood cells. "Driven by HSP, our MYCN transgenic zebrafish also showed increased numbers of peripheral myeloid cells, anemia and vast myeloid blasts infiltrated in spleen, liver and kidney." (PMID 23554972, 2013).
bone marrow disease (2 papers, 2010 to 2015). "One case, stage 4 MYCN amplified, progressed after a good initial response to chemotherapy and died of refractory bone marrow disease (case #6)." (PMID 20950435, 2010).
brainstem glioma (2 papers, 2016 to 2018). "The subset of brainstem gliomas with MYCN amplification may also be susceptible to bromodomain inhibition." (PMID 27556016, 2016). "In contrast, VUMC-10 is a MYCN-amplified, histone wild-type brainstem glioma." (PMID 30577869, 2018). "Amplification of MYCN was found to define a subset of pediatric DIPG in one genomic analysis; the frequency of this finding in adult brainstem glioma is also unknown." (PMID 27556016, 2016).
duodenal atresia (2 papers, 2022). Duodenal atresia is an embryopathy of the cranial intestine that leads to a complete absence of the duodenal lumen. "MYCN is significantly associated with Feingold syndrome-1 (FGLDS1), which is characterized by esophageal and duodenal atresia, microcephaly, limb malformation, and mental retardation." (PMID 35045821, 2022).
eye tumor (2 papers, 2020 to 2025). "CNA analysis of the primary ocular tumor sample from Patient 2 using Oncoscan showed a high-level (>60 copies) 2p focal amplification harboring MYCN and no apparent copy number alterations in chromosome 13." (PMID 32971811, 2020).
ganglioglioma (2 papers, 2025). A well differentiated, slow growing neuroepithelial neoplasm composed of neoplastic, mature ganglion cells and neoplastic glial cells. "MET amplification was found in one case of ganglioglioma, while two cases carried amplifications of MYCN, including a case of IDH-mutant and 1p/19q co-deleted oligodendroglioma and a case of IDH-wild-type diffuse astrocytic tumor." (PMID 41517303, 2025).
germ cell tumor (2 papers, 2025). A benign or malignant, gonadal or extragonadal neoplasm that originates from germ cells. "ARID3B is frequently co-expressed with MYCN in germ cell tumors, ESCs, and testis—cell types associated with pluripotency." (PMID 39999848, 2025). "This sample was MYCN amplified and associated with Superfamily “Germ cell tumours” (CS < 0.4)." (PMID 40713849, 2025). "This case was reported as an INSS Stage 1 and COG low risk, hyperdiploid, lacking MYCN amplification, with undifferentiated or poorly differentiated histology, and was associated with the Superfamily “Germ Cell Tumours” (CS of 0.66)." (PMID 40713849, 2025).
insulinoma (2 papers, 2016 to 2021). "The only other MYCN-driven animal model of MYCN-induced PanNETs was described in zebrafish, yet the developing tumors were similar to human insulinomas." (PMID 27769070, 2016).
lentivirus infection (2 papers, 2019 to 2024). Virus diseases caused by the Lentivirus genus. "After knockdown of HSF1 with siRNAs, MYCN expression was restored by lentivirus infection." (PMID 39248163, 2024). "MYCN mRNA and protein levels were decreased after knockdown of HSF1 and recovered after lentivirus infection." (PMID 39248163, 2024).
Li-Fraumeni syndrome (2 papers, 2016 to 2018). "Multiple amplicons in a SHH setting usually associate GLI2 with MYCN and may indicate Li-Fraumeni syndrome, which is linked to a dismal prognosis." (PMID 26857864, 2016). "Interestingly, MYCN is a frequent driver gene in SHH MBs developed by Li-Fraumeni Syndrome patients, for which all analyzed tumors show chromothripsis." (PMID 30420702, 2018).
lymphocytic leukemia (2 papers, 2011 to 2020). "The R2 database, containing 105 NB patients, showed an inverse correlation between MYCN mRNA and deleted in lymphocytic leukemia (DLEU) 2, a host gene of miR‐15." (PMID 31637848, 2020).
ovarian tumor (2 papers, 2021 to 2023). "In addition to MYC, copy-number amplification and/or overexpression of MYCL1 and MYCN have also been reported in ovarian tumors." (PMID 33671595, 2021). "First, we screened a panel of DUBs belong to ovarian tumor (OTU) superfamily and the ubiquitin C-terminal hydrolase (UCH) superfamily by co-transfecting them into 293T cells with MYCN." (PMID 37543638, 2023).
renal carcinoma (2 papers, 2017 to 2023). A carcinoma arising from the epithelium of the renal parenchyma or the renal pelvis. "CDKN2A can accelerate the invasion and migration of renal cancer cells and MYCN inhibits the invasion and migration of renal cancer cells through wound healing assay and transwell invasion assays." (PMID 37878133, 2023). "CDKN2A promotes the migration of renal cancer cells, while MYCN inhibits their migration." (PMID 37878133, 2023).
Sepsis (2 papers, 2008 to 2026). Sepsis is defined as life-threatening organ dysfunction caused by a dysregulated host response to infection. "Of the 123 stage 2 patients with normal MYCN, 1 died of sepsis and 22 relapsed, 8 of whom died (RFS 82.8%, 95% CI: 76.2–89.5; OS 93.2%, 95% CI: 88.7–97.8)." (PMID 18766186, 2008).
T-cell lymphoma (2 papers, 2014 to 2023). "For example, MYCN locus is a common target of retroviral integration in mouse T-cell lymphoma, and transgenic mice that overexpressed MYCN (Eμ-N-myc genes) develop pre-B and B lymphoid malignancies." (PMID 24334727, 2014).
uterine carcinosarcoma (2 papers, 2024). A usually aggressive malignant neoplasm arising from the uterine corpus and less often the cervix.
Zika virus infection (2 papers, 2018). "On the other hand, ZIKV infection was found to inhibit the expression of MYC, MYCN and NKX2.3 transcription factors, which play roles in cell cycle, proliferation and cellular development." (PMID 30046058, 2018).
Allergy (1 paper, 2022). An allergy is an immune response or reaction to substances that are usually not harmful. "Neither the gene MYCN proximal to the genetic variants associated with asthma in our study, nor its respective locus, have previously been associated with asthma or allergy in the literature." (PMID 35461280, 2022).
asthma (1 paper, 2022). "Studying GWAS-nominated loci of LC and COPD, this study allowed to identify one new asthma locus (2p24.3 locus near MYCN gene)." (PMID 35461280, 2022).
bone tumors (1 paper, 2023). "In bone tumors, the MSKCC cohort had significantly fewer mutations in MAP3K1, CREBBP, MCL1, GNAQ, MEF2B, MYCN, SDHA, and SMARCA4." (PMID 37546405, 2023).
central neurocytoma (1 paper, 2022). A benign brain tumor composed of neural elements which most often arise from the SEPTUM PELLUCIDUM and the walls of the lateral ventricles. "A microarray-based comparative genomic hybridization investigation revealed distinct profiles, with loss and gain of multiple chromosomal loci, which concluded that MYCN gene amplification, together with loss of BIN1 expression, were typical of central neurocytoma." (PMID 35663322, 2022).
choroid plexus carcinoma (1 paper, 2026). A malignant neoplasm arising from the choroid plexus. "By contrast, choroid plexus carcinoma models driven by MYCN showed a relatively flat genome with recurrent loss of chromosome 1, which did not match the severely unbalanced genomes of human choroid plexus carcinoma." (PMID 41381884, 2026).
cutaneous melanoma (1 paper, 2023). A primary melanoma arising from atypical melanocytes in the skin. "Although Mycn can replace the Myc functional role in murine lymphocyte development and activation, the present data indicates that MYC and MYCN have opposing relationships with the expression of T cell markers and functional genes in cutaneous melanomas." (PMID 36768931, 2023). "TCGA data for additional cancers with RNAseq and survival data were surveyed to determine whether the MYCN correlations identified for cutaneous melanoma extend to other tumor types." (PMID 36768931, 2023).
developmental delay (1 paper, 2024). "In contrast, RAB14 and MYCN, other risk genes for developmental delay, exhibited peaks in later stages, which coincided with neuroblast differentiation into excitatory neurons during the fetal second trimester." (PMID 39363111, 2024).
Duchenne muscular dystrophy (1 paper, 2023). Duchenne muscular dystrophy (DMD) is a neuromuscular disease characterized by rapidly progressive muscle weakness and wasting due to degeneration of skeletal, smooth and cardiac muscle. "We also tested the antineoplastic activity of piperacetazine in a second mouse model where PAX3::FOXO1 is expressed under a doxycycline-regulated promoter in an immortalized human Duchenne muscular dystrophy myoblast cell line (Dbt) expressing MYCN." (PMID 37732905, 2023).
embryonal rhabdomyosarcoma (1 paper, 2023). A poorly circumscribed morphologic variant of rhabdomyosarcoma. "Similarly, patient SARC-0027 was diagnosed with embryonal rhabdomyosarcoma with MYCN gain at diagnosis." (PMID 37189699, 2023).
endometrial cancer (1 paper, 2017). Primary or metastatic malignant neoplasm involving the endometrium (mucous membrane that lines the endometrial cavity). "Amplification and overexpression of MYCN has not been described for human uterine cancer but was noted along with ODC1 as being amplified in rat endometrial cancer." (PMID 29240775, 2017).
Esophageal atresia (1 paper, 2021). A developmental defect resulting in complete obliteration of the lumen of the esophagus such that the esophagus ends in a blind pouch rather than connecting to the stomach. "We present an occurrence of esophageal atresia with tracheoesophageal fistula in siblings from a three-generation family affected by variable expressivity of MYCN p.(Ser90GlnfsTer176) mutation." (PMID 34926353, 2021).
Gorlin syndrome (1 paper, 2019). "We tested this idea, first by transducing NES cells with MYCN and second by deriving NES cells from patients with Gorlin syndrome, bearing germline mutations in PTCH1, and in each case performing orthotopic transplantation in mice." (PMID 31204176, 2019).
holoprosencephaly (1 paper, 2022). Holoprosencephaly (HPE) is a complex brain malformation resulting from incomplete cleavage of the prosencephalon, occurring between the 18th and 28th day of gestation, and affecting both the forebrain and face, which results in neurological manifestations and facial anomalies of variable severity. "Both TGIF and ZIC2 are mutated in holoprosencephaly, a disorder caused by a failure in embryonic forebrain development, whereas MYCN mutations cause Feingold and megalocephaly syndromes, which are associated with reduced and increased brain size, respectively." (PMID 35438231, 2022).
Hyperglycemia (1 paper, 2025). An increased concentration of glucose in the blood. "The low expression of MYCN in T2DM may be due to a protective mechanism of the body under hyperglycemia." (PMID 39966875, 2025).
interstitial lung disease (1 paper, 2014). A diverse group of lung diseases that affect the lung parenchyma. "Notably, average MYCN mRNA levels also are elevated in individuals with interstitial lung disease compared to controls and COPD." (PMID 24475138, 2014).
male infertility (1 paper, 2023). The inability of the male to effect fertilization of an ovum after a specified period of unprotected intercourse. "Meanwhile, only one gene MYCN may be associated with male infertility." (PMID 37684669, 2023).
megalencephaly-polydactyly syndrome (1 paper, 2024). "Recently, we established the megalencephaly-polydactyly syndrome (OMIM #620748) in three individuals harboring heterozygous gain-of-function (GoF) MYCN variants, namely p.(Thr58Met) and p.(Pro60Leu), that helped understanding the MYCN’s roles in human development." (PMID 38884091, 2024). "MYCN variants have been linked to two distinct human developmental diseases: FS1 and megalencephaly-polydactyly syndrome." (PMID 38884091, 2024). "We previously established the GoF MYCN-induced megalencephaly-polydactyly syndrome." (PMID 38884091, 2024).
myeloid malignancies (1 paper, 2015). "Several zebrafish models associated with myeloid malignancies have been previously reported, including transgenic zebrafish that exhibit K-RASG12D, NUP98-HOXA9, Stat5 (H298R), Stat5 (N714F), NPM1, tel-jak2a, AML1-ETO, FLt3-ITD, FLT3-TKD (D835Y), MYCN, or MOZ/TIF2 expression." (PMID 26064935, 2015).
myocardial infarction (1 paper, 2025). Gross necrosis of the myocardium, as a result of interruption of the blood supply to the area, as in coronary thrombosis. "Downregulation of the lncRNA myocardial infarction-associated transcript (MIAT) reduces N-Myc expression and the MYCN target gene ODC1 in MNA-NB and inhibits glycolysis, supporting its potential as a therapeutic target." (PMID 41244073, 2025).
non-Hodgkin lymphoma (1 paper, 2014). Distinct from Hodgkin lymphoma both morphologically and biologically, non-Hodgkin lymphoma (NHL) is characterized by the absence of Reed-Sternberg cells, can occur at any age, and usually presents as a localized or generalized lymphadenopathy associated with fever and weight loss. "This compound class has been reported to be active in a number of diseases dependent on either MYC or MYCN, including neuroblastoma, medulloblastoma, multiple myeloma, and non-Hodgkin Lymphoma (NHL), to name a few." (PMID 25072021, 2014).
osteoporosis (1 paper, 2024). A condition of reduced bone mass, with decreased cortical thickness and a decrease in the number and size of the trabeculae of cancellous bone (but normal chemical composition), resulting in increased fracture incidence. "To identify potential targets for treating osteoporosis, we have verified the ferroptosis-related KMT2D gene and MYCN gene, both of which are drivers of ferroptosis." (PMID 39867575, 2024).
Pca (1 paper, 2023). "NVP-2, MC180295, fadraciclib, KB-0742, LZT-106, and 21e have been developed, and the inhibitory effects of NVP-2 on BRAFwt/NRASwt/NF1wt cutaneous and uveal melanomas, MC180295 on CRC, fadraciclib on MYCN-amplified Kelly NB tumor, KB-0742 on Pca, LZT-106 on CRC, and 21e on NSCLC, have been reported." (PMID 37272701, 2023).
pineoblastoma (1 paper, 2025). Pineoblastoma is a rare, malignant type of supratentorial primitive neuroectodermal tumor (sPNET), found mainly in children (less than 10% of cases are reported in adults), and located in the pineal region of the brain but that can metastasize along the neuroaxis. "Although there is not much research on MYCN amplification in pineoblastoma, studies have shown that MYCN can be highly expressed in this tumor subtype even without gene amplification." (PMID 40365336, 2025).
retinal cancer (1 paper, 2025). A malignant neoplasm involving the retina.